RAET1G (retinoic acid early transcript 1G)
Description:
[Isoform 1]: Binds and activates the KLRK1/NKG2D receptor, mediating natural killer cell cytotoxicity. [Isoform 3]: Down-regulates the expression of KLRK1 and stimulates natural killer cells to secrete IFNG. [Isoform 2]: Stimulates natural killer cells to secrete IFNG.
Synonyms: ULBP5
Tractability: Antibody: UniProt places it where antibodies can reach, with high confidence; its Gene Ontology location is reachable by antibodies, with high confidence; UniProt predicts a signal peptide or a membrane-spanning region; the Human Protein Atlas places it where antibodies can reach. PROTAC: ubiquitination databases record sites on it.
Gene: Protein-coding gene on chromosome 6 (149,916,878 to 149,923,121, reverse strand). Ensembl gene ENSG00000203722.
Subcellular location: Cell membrane (Isoform 1); Endoplasmic reticulum; Secreted (Isoform 2)
Subcellular location (Human Protein Atlas): Plasma membrane; Vesicles; Predicted to be secreted
Pathways (Reactome):
Metabolism of proteins: Post-translational modification: synthesis of GPI-anchored proteins
Gene Ontology:
Molecular function: natural killer cell lectin-like receptor binding; protein binding; receptor ligand activity
Biological process: natural killer cell mediated cytotoxicity; positive regulation of natural killer cell cytokine production; antigen processing and presentation of endogenous peptide antigen via MHC class I via ER pathway, TAP-independent; antigen processing and presentation of endogenous peptide antigen via MHC class Ib; positive regulation of T cell mediated cytotoxicity; signal transduction
Cellular component: endoplasmic reticulum; extracellular region; plasma membrane; external side of plasma membrane
Genetic constraint (gnomAD): Loss-of-function variants: 25 observed, 30.17 expected, observed/expected ratio (o/e) 0.83, 90% interval 0.6 to 1.16. The upper end of that interval is the gene's LOEUF score, 1.16, which puts it in group 5 of 6, group 1 being the genes least tolerant of losing a copy. Missense variants: 434 observed, 436.17 expected, observed/expected ratio (o/e) 1, 90% interval 0.92 to 1.08. Synonymous variants: 167 observed, 161.14 expected, observed/expected ratio (o/e) 1.04, 90% interval 0.91 to 1.18.
Homologues: Orthologues: chimpanzee RAET1G (95% identical), pig ULBP1 (29% identical), mouse Ulbp1 (16% identical), zebrafish mhc1lda (11% identical), zebrafish mhc1lla (10% identical), zebrafish mhc1lfa (10% identical), zebrafish mhc1lga (10% identical), zebrafish mhc1laa (10% identical), zebrafish si:dkey-52p2.5 (10% identical), zebrafish mhc1lja (9% identical), tropical clawed frog mhc1-uea (9% identical), zebrafish mhc1lba (8% identical), and 1 more. Paralogues in human: ULBP2 (65% identical), RAET1L (64% identical), ULBP1 (44% identical), ULBP3 (40% identical), RAET1E (23% identical), HLA-E (19% identical), HLA-A (19% identical), HLA-B (18% identical), HLA-C (18% identical), HLA-F (18% identical), HLA-G (18% identical), MR1 (16% identical), and 10 more.
Diseases named in the same sentence as RAET1G in open-access papers:
RAET1G is named in the same sentence as 12 diseases in open-access papers, as found by Europe PMC text mining. Sharing a sentence is not in itself a finding about the gene and the disease. The quoted sentences say what the papers report.
breast carcinoma (2 papers, 2021 to 2022). "Except for CCL19, RAET1G, IL12B, CXCL13, CCL22, and NOS1 were significantly highly expressed in breast cancer at the mRNA level." (PMID 36292723, 2022).
cervical cancer (2 papers, 2014 to 2021). A primary or metastatic malignant neoplasm involving the cervix. "Approximately one third (7 of 19; SPRR2G, RAET1G, FOXA2, BNIPL, LOR, LCE2B, and LCE1B) had expression that was highest among the NED/Stage1/Stage2 cluster, lower in the premalignant cluster, and even lower in Stage 3 cervical cancer tissue." (PMID 34944802, 2021).
colorectal cancer (1 paper, 2023). A primary or metastatic malignant neoplasm that affects the colon or rectum. "Early reports indicated that elevated MICA or MICA/B and RAET1G (ULBP5) were linked to improved prognosis in colorectal cancer." (PMID 37626965, 2023).
colorectal tumors (1 paper, 2015). "High expression of MIC or RAET1G has been shown to be associated with prolonged survival of patients with colorectal tumors." (PMID 25789015, 2015).
tumor (9 papers, 2009 to 2025). "ULBP2 and RAET1G (which encodes ULBP5), which share the highest sequence homology with RAET1L, also exhibit similar expression profiles within the tumor microenvironment." (PMID 40116579, 2025). "The importance of ligands expression for tumor cell recognition by NK cells is a key factor for anti-tumor immune response, as illustrated by the strong prognostic value of MICA/MICB, RAET1G, and ULBP2 expression in colorectal cancer and breast cancer." (PMID 24715892, 2014). "RAET1G also represents a potential avenue for cancer therapy, for example by inducing its expression on NKG2D ligand negative tumours or as a target for anti-cancer monoclonal antibodies." (PMID 19223974, 2009).
RAET1G also shares sentences with these, for which no sentence is quoted: cancer (3 papers); Alzheimer disease (1); breast tumor (1); celiac disease (1); cervical intraepithelial neoplasia (1); lung carcinoma (1); sarcoma (1).